MAVS (mitochondrial antiviral signaling protein)
Diseases named in the same sentence as MAVS in open-access papers (continued):
Sharing a sentence is not in itself a finding about the gene and the disease.
viral infection (continued). "Finally, we looked at RIG-I activation by fluorescence microscopy and we observed an enhanced punctuated staining of RIG-I upon Sp1 induction (-DOX: 91±7% vs +DOX: 42,2±11,7%), suggesting the formation of RIG-I aggregates as it was described for MAVS activation in a context of viral infection." (PMID 25738304, 2015). "Thus, degradation of MAVS by NSP1 not only affects its interaction with downstream molecules (TBK1) but also inhibit downstream aggregate formation on mitochondrial membrane in response to virus infection." (PMID 24643253, 2014). "A similar scenario is proposed here where, in response to viral infection, the association of TRAF3 with complexes containing p115 and Sec16A at the ER-to-Golgi vesicular pathway may play an important role in positioning TRAF3 with MAVS." (PMID 22792062, 2012). "However, during virus infection, MAVS is proteolysed by a proteasome-dependent PCBP2/AIP4 axis." (PMID 20532218, 2010). "Thus, it is an interesting working hypothesis that NOX2-dependent mechanism might permit expression of MAVS during virus infection to regenerate the pool of available MAVS in the cell to mount a sustained antiviral response." (PMID 20532218, 2010). "Upon viral infection, activated TBK1 phosphorylates STING at a pLxIS motif, which is also present in MAVS." (PMID 40483467, 2025). "Upon viral infection, cytosolic RIG-I-like receptors recognize viral RNA and activate innate immune responses through the mitochondrial antiviral-signaling protein (MAVS), leading to type I interferon (IFN) production and apoptosis." (PMID 40837220, 2025). "NLRX1 negatively regulates MAVS-mediated IRF3 activation and type I IFN induction during viral infection." (PMID 41463370, 2025). "Viral infections have been noted to induce OTUD4 expression via IRF3/7, which subsequently binds to mitochondrial antiviral signaling protein (MAVS), inhibiting its ubiquitination." (PMID 40277358, 2025). "For example, cytosolic sensors can detect viral RNA and activate a protein, MAVS, on the outer mitochondrial membrane that induces Type I interferon (INF) production, which is essential in the immune response to viral infections." (PMID 41517335, 2025). "Upon detecting a viral infection, these RLRs form a complex with their adaptor protein, the mitochondrial antiviral signaling protein (MAVS, also referred to as IPS-1, CARDIF, or VISA), which is located on the outer mitochondrial membrane and peroxisomes." (PMID 41008646, 2025). "During viral infection, termination of RIG-I mediated mitochondrial antiviral signaling proteins (MAVS) signaling blocked apoptosis and type I IFN signaling." (PMID 41171885, 2025). "RIG-I activates downstream signaling pathways, including those involving MAVS (mitochondrial antiviral signaling protein) and the NF-κB and IRF3 transcription factors, to orchestrate the host’s defense against viral infections." (PMID 40214229, 2025). "After viral infection, PRMT9 dissociates from MAVS on the mitochondria, allowing MAVS aggregation and activation." (PMID 40842475, 2025). "Yet, viral infection induced an IRF3/7-dependent up-regulation of OTUD4, which bound to MAVS to remove K48-Ub, thereby maintaining MAVS stability and promoting innate anti-viral signaling." (PMID 40469292, 2025). "Mitochondrial antiviral signaling (MAVS) was first discovered as an activator of NF-κB and IRF3 in response to viral infection in 2005." (PMID 40040697, 2025). "Upon viral infection, STAT2 translocates to mitochondria, where it is targeted for degradation by the viral degradasome formed by viral proteins and MAVS." (PMID 39655955, 2025). "Mitochondrial Antiviral Signaling Protein (MAVS) is a pivotal adaptor protein in the innate immune response, mediating the activation of NF-κB and type I interferon signaling pathways during viral infections." (PMID 40842475, 2025).
viral infection (continued). "Virus infection activates receptors such as RIG‐I, which leads to the recruitment of the adaptor protein MAVS to the RIG‐I‐like receptor (RLR) signaling complex." (PMID 40548900, 2025). "A canonical antiviral protein, mitochondrial antiviral-signaling protein (MAVS), which orchestrates the host innate immune response to RNA virus infection, has been found to interact with Rac1 during viral infection." (PMID 40316910, 2025). "Functional prion-like protein aggregations, such as the mitochondrial adaptor protein MAVS and the inflammasome component protein ASC, have been identified to play a protective role in viral infections in mammalian cells." (PMID 39194237, 2024). "During viral infections, RNase L has been demonstrated to promote NLRP3 inflammasome activation through a signaling pathway involving DHX33 and MAVS, leading to the production of IL-1B in bone marrow-derived dendritic cells." (PMID 38473966, 2024). "Subsequently, MAVS connects RIG-I/MDA5 to IKK and TBK1/IKKε, activating IRF3 and NFκB—the two crucial components of the pathway that induce IFN in response to viral infection." (PMID 39335111, 2024). "Upon virus infection, activated RIG-I participates in downstream signaling pathways by interacting with MAVS." (PMID 39470258, 2024). "The collective findings revealed that DDX11 was dependent on MAVS to accumulate in mitochondria after viral infection, which enhanced the formation of the RIG-I-MAVS complex." (PMID 39470258, 2024). "Viral infection triggers the activation of RIG-I/MDA5, which, in turn, leads to the recruitment of MAVS through tandem Activation and Recruitment Domains (CARDs)." (PMID 39335111, 2024). "Upon virus infection, viral RNA recognizes and binds receptors such as RIG-I and MAD5 and then binds to MAVS in peroxisomes (peroxisome MAVS), leading to the IRF1-dependent production of type III IFNs to counteract viral infection." (PMID 39205283, 2024). "RNA viruses such as Sendai virus (SeV) and VSV trigger the activation of TRIM21, interacting with MAVS and catalyzing MAVS polyubiquitination, activating IRF3, and suppressing viral infections." (PMID 39335111, 2024). "A fluorescence resonance energy transfer (FRET) assay further confirmed that there was a strong interaction between MAVS and ZDHHC12 upon viral infection." (PMID 39621307, 2024). "Upon sensing viral infections, RIG-I-like receptors (RLRs) are activated and bind to the signaling adapter MAVS on the mitochondrial surface." (PMID 39386614, 2024). "MAVS, when activated, forms filaments approximately 400 nm in length containing hundreds of MAVS molecules, which is observed in this study using SR-SIM in A549, BMDM, and MEF cells with virus infection or poly(I:C) transfection." (PMID 39141356, 2024). "Our findings revealed new mechanisms by which SAMHD1 suppresses IFN-I induction through the MAVS, IKKε, and IRF7 signaling axis in the context of viral infection, which help better understand the role of SAMHD1 in innate immunity." (PMID 37328105, 2023). "Although interferon-stimulated genes (ISGs) were not expected to be differentially expressed in response to the viral infection, ISG expression can be induced by an IFNAR-independent pathway, such as the downstream of MAVS signaling in myeloid dendritic cells." (PMID 37191498, 2023). "Caspase-3 prevents the overproduction of type I IFN during viral infection by cleavage of cGAS, IRF-3, and MAVS." (PMID 37692170, 2023). "TRAF3IP3 binds to MAVS and facilitates its recruitment of downstream TRAF3 during viral infection, thereby promoting antiviral response." (PMID 37563140, 2023). "Recently, we found that MARCH5 regulates the activity of MAVS and RIG-I, two key proteins that play a role in the innate immune response to dsRNA virus infection, by inducing their degradation." (PMID 38040710, 2023).
viral infection (continued). "All three RIG-I orthologs were capable of binding dsRNA, are in their function partially dependent on the 5’-triphosphate RNA end, are signaling via MAVS, and can trigger the induction of IFN and other cytokines in response to viral RNA or virus infection." (PMID 37728614, 2023). "After viral infection activates RLR, RNF34 promotes the polyubiquitination of MAVS, which is then recognized by NDP52 and degraded by autophagy." (PMID 37442062, 2023). "Upon viral infection, RLRs induce mitochondrial antiviral signaling protein (MAVS) and Interferon regulatory factor 3 (IRF3), and MAVS is attached to the mitochondrial membrane." (PMID 36851739, 2023). "We then went to examine how the interaction between MAVS and WDR77 is modulated during viral infection." (PMID 37563140, 2023). "MAVS is located on the outer membrane of mitochondria (OMM) and is known to promote proinflammatory signaling pathways following viral infections." (PMID 37528226, 2023). "Immune responses to viral infection are mediated by various cytosolic DNA- and RNA-sensing pathways, including cGAS-STING and RIG-I/MAVS." (PMID 38161589, 2023). "In response to virus infection, WDR77 is recruited to MAVS to prevent the formation of its prion-like aggregates and thus downregulate RIG-I-MAVS signaling in cells." (PMID 37563140, 2023). "Then, nucleic acid sensors, such as STING, MAVS, and RIG-I, detect the viral genome and induce immune signals in response to virus infection." (PMID 36675197, 2023). "Coincidentally, STING is known to bind mitochondrial antiviral signaling protein (MAVS) on MAM, thereby increasing the interferon response to viral infection." (PMID 37781026, 2023). "In the viral infection, RIG-I recognizes viral double-stranded RNA to activate RIG-I/MAVS antiviral functions, induce type I interferon production." (PMID 37901251, 2023). "Upon viral infection, PRMT9 dissociates from the mitochondria, leading to MAVS activation and IFN-I stimulation." (PMID 37928266, 2023). "Our findings provide insights into the TLR3-TRIF signaling pathway and MAVS in viral infections, and suggest TLR3-mtROS as a therapeutic target for the treatment of airway inflammatory and viral infectious diseases." (PMID 38203397, 2023). "Upon viral infection, the CARD domain of MAVS interacts with the CARD domains of retinoic acid-inducible gene I (RIG-I) or melanoma differentiation associated gene 5 (MDA5), initiating downstream signaling cascades." (PMID 37901251, 2023). "For instance, OTUD1 increases Smurf1 expression levels to promote degradation of the MAVS/TRAF3/TRAF6 signalosome and inhibit the innate immune response to viral infection." (PMID 35280681, 2022). "STING (MITA, mediator of IRF-3 activator) is a protein that binds to MAVS and is crucial for IFN production and NF-κB activation after viral infection." (PMID 36248895, 2022). "Collectively, these data suggest that TRIM18 recruits PPM1A to dephosphorylate TBK1 for its inactivation and blocks interaction of TBK1 with its upstream adaptors MAVS and STING for signal transduction during virus infection." (PMID 35909127, 2022). "p62 has been reported to control IFN antiviral responses by promoting autophagic degradation of several key factors in the IFN pathway, including RIG-I, cGAS, MAVS, and IRF3 during viral infection." (PMID 35865923, 2022). "During viral infection, viral PAMP is recognized by RLRs receptors and binds to MAVS on the outer mitochondrial membrane to activate MAVS, which induce IFN-I secretion by recruiting and activating TRAF6, TBK1, and TABS." (PMID 36590405, 2022). "Second, TRIM18 interacts with TBK1 and blocks its interactions with upstream adaptors MAVS and STING for preventing signal transduction during virus infection." (PMID 35909127, 2022). "During viral infection, PCBP2 is induced to recruit the HECT domain-containing E3 ligase AIP4 by interacting with MAVS." (PMID 36505476, 2022).
viral infection (continued). "In response to viral infection, TRAF3IP3 bridges TRAF3 and MAVS leading to interferon production, indicating it’s probably strong relationship with Covid-19 disease." (PMID 35694544, 2022). "MAVS is well recognized as a key signaling protein downstream of viral RNA sensors RIG-1 and MDA5 during viral infection." (PMID 35844503, 2022). "As a regulator of Mitochondrial antiviral signaling protein (MAVS) aggregation, TRIM31 can be recruited to mitochondria after viral infection and specifically regulate antiviral signaling mediated by RIG-I-like receptor (RLR) pattern-recognition receptors." (PMID 36620540, 2022). "Upon virus infection, PRMT9 dissociates from the mitochondria, leading to the aggregation and activation of MAVS." (PMID 36028484, 2022). "According to research, mitochondrial antiviral signaling (MAVS) mediated the activation of NF-κB and IRF 3 in response to viral infection and was required for upstream of the phosphorylation of IRF 3 and IκB and downstream of RIG-I." (PMID 36139261, 2022). "During the virus infection, MARCH5 interacts with activated MAVS oligomer and decreases MAVS-mediated IFN signaling by K48-linked ubiquitination and degradation of MAVS." (PMID 35008917, 2022). "The strong dependence of chromatin accessibility on MAVS and IRF3 supported that extranuclear signaling pathways conferred a requirement for remodeling of chromatin after viral infection." (PMID 35658050, 2022). "Rotaviruses encode multiple viral proteins that inhibit innate immune responses by degrading interferon regulatory factors (IRFs) and mitochondrial antiviral-signaling protein (MAVS), thus facilitating efficient virus infection and replication." (PMID 35098923, 2022). "Upon viral infection, OTUD4 expression is induced to quickly stabilize MAVS, preparing it for timely response to infection." (PMID 35795661, 2022). "In the case of the RLR–MAVS complex, the adaptor MAVS was reported to induce the formation of large, prion-like aggregates to activate IRF3 and propagate interferon-mediated response upon viral infection." (PMID 35979366, 2022). "TRAF3IP3 is a critical regulator for the downstream RIG-I/MDA-5 signaling pathway, and it accumulates on mitochondria in response to viral infection, driving TRAF3 to MAVS for TBK1-IRF3 activation." (PMID 35885892, 2022). "TRIM18 was shown to recruit protein phosphatase 1A (PPM1A) to dephosphorylate TBK1, which inactivates TBK1 and blocks its interactions with upstream adaptors MAVS and STING, thereby dampening type I IFN mediated antiviral signaling during viral infections." (PMID 35909127, 2022). "As a key, in type I-IFN signaling during viral infection, pathogen-derived nucleic acid activates STING and MAVS, which recognize intracellular DNA and RNA, respectively." (PMID 36059459, 2022). "MFN2 appears to be a key regulator of innate immunity, as it interacts with MAVS, NLRP3, and various other signaling molecules during viral infections." (PMID 34482801, 2021). "This is because, upon the virus infection, expression of the type-I IFN pathway-related molecules, including MAVS, tends to increase due to the activation of the transcription and translation machinery of those genes in the cytoplasm." (PMID 34578357, 2021). "To this end, we examined the ability of TRAF3 to interact with both MAVS and TBK1 upon viral infection in HEK293T cells in which endogenous TFG was knocked down with a TFG-specific short interfering RNA (siRNA, siTFG)." (PMID 33411856, 2021). "Our results detail the functional role of TFG in innate immunity as an ER-to-Golgi resident protein which allows TRAF3 to interact with upstream adapter protein MAVS and downstream kinase TBK1 resulting in activation of TBK1 upon viral infection." (PMID 33411856, 2021). "After viral infection, IKKε mediates FAF1 phosphorylation and, following acetylation, degradation and consequent enhancement of the MAVS antiviral signaling." (PMID 34566944, 2021).
viral infection (continued). "Upon viral infection, RIG-I recognizes viral RNA in a 5′-triphosphate-dependent manner and initiates an antiviral signaling cascade for MAVS/VISA/IPS-1/Cardif." (PMID 33921888, 2021). "We identify TFG as being part of a molecular complex comprised of at least MAVS, TRAF3 and TBK1 and requirement of TFG in the interactions of TRAF3 with TBK1 and MAVS upon viral infection." (PMID 33411856, 2021). "Upon viral infection, USP18 is critical for the re-localization of TRIM31 from the cytoplasm to mitochondria and the interaction between TRIM31 and MAVS." (PMID 34016972, 2021). "To assess changes in RIG-I and MDA5-mediated signaling cascades upon viral infection, we analyzed changes in the phosphorylation of TBK1 and IRF3, which are the downstream events of MAVS activation and hall marker of interferon pathway activation." (PMID 34016972, 2021). "Upon viral infection, RIG-I and MDA5 bind to MAVS, thereby activating downstream signal transduction." (PMID 34782737, 2021). "We observed that the interaction between MAVS and TRIM31 following viral infection was significantly impaired in Usp18−/− MEFs compared with Usp18+/+ MEFs." (PMID 34016972, 2021). "The PLK1–MAVS interaction, identified through a yeast two-hybrid screen, interferes with the binding of MAVS with TRAF3 and attenuates IFN signaling during viral infection as well as during the G2/M phase of the cell cycle." (PMID 32117959, 2020). "After recognizing viral infection, the activated RIG-I and MDA5 release their CARD domain to interact with the same domain of the mitochondrial anti-viral signaling (MAVS, also known as IPS-1, VISA, or CARDIF) protein." (PMID 33381104, 2020). "Whereas upon viral infection, FGF2 suppresses antiviral signaling by inhibiting the interaction of activated RIG-1 with downstream mitochondrial antiviral-signaling protein (MAVS) and type I interferon production." (PMID 32300593, 2020). "Stimulatory phosphorylations were identified by LC-MS/MS analyses at serine residues 442, 444, and 44 in the C terminus of MAVS, which are phosphorylated by TBK1 and IKKβ upon viral infection." (PMID 32117959, 2020). "During viral infection, TTLL12 expression is reduced, thereby releasing the block in MAVS-mediated activation of the immune response." (PMID 32536927, 2020). "In sum, our study reveals CORT as an essential regulator of MAVS-dependent IFN-β response, in response to virus infection under stress status." (PMID 32943610, 2020). "Dendritic cells (DCs) detect viral infections via cytosolic RIG-I like receptors (RLRs) RIG-I and MDA5 leading to MAVS-induced immunity." (PMID 32038656, 2020). "For example, HCV NS5A localizes to the endoplasmic reticulum during viral infection, while the NS5A binds to LRPPRC on mitochondria to inhibit the MAVS-regulated antiviral signaling during HCV infection." (PMID 31937766, 2020). "Viral infection upregulates the expression of TRIM21, thereby promoting the recruitment of TBK1 to MAVS and enhancing downstream signaling." (PMID 32536927, 2020). "The expression of UBXN1 is strongly upregulated late during viral infection and it competes with TRAF3/TRAF6 for binding to MAVS (amino acids 455–460), thus blocking MAVS signaling." (PMID 32536927, 2020). "Here we show that RNF115 plays dual roles in response to RNA or DNA virus infections by catalyzing distinct types of ubiquitination of MAVS and MITA at different phases of viral infection." (PMID 33139700, 2020). "Upon virus infection, viral RNAs interacted with the RD and the helicase domain of RIG-I, which in turn exposed the CARDs for MAVS interaction, thereby triggering antiviral responses." (PMID 31849979, 2019). "THOC7 interacted with MAVS, TBK1, IKKε, and IRF3 and, notably, the interaction was decreased with MAVS, but increased with TBK1 after virus infection, indicating that THOC7 have a significant function by targeting TBK1 in the antiviral response." (PMID 30769920, 2019).